CD4 (CD4 molecule)
Diseases named in the same sentence as CD4 in open-access papers (continued):
Sharing a sentence is not in itself a finding about the gene and the disease.
tumor (continued). "DCs cocultured with CTLA-4+ breast cancer cells expressed lower amounts of HLA-DR and costimulatory molecules, inhibited CD4+ and CD8+ T cell differentiation, and facilitated tumor growth." (PMID 35310881, 2020). "Compared to GB/PC-KO, GB/PC-WT mice displayed increased IL-2 levels, tumor proliferation, FoxP3+PD-1+CTLA-4+ TILs, higher Tgfβ, and Il10 mRNA expression levels, and a CD4+/CD8+ ratio of 4:1." (PMID 33335860, 2020). "The repression of tumour growth was accompanied by the infiltration of CD4+ and CD8+ effector/memory (CD44hiCD62Llo) T cells into tumours." (PMID 31803974, 2020). "Our study provides novel evidence of CD4+ and CD8+ T-cell–intrinsic effects of Yap on T-cell activation and tumor infiltration." (PMID 31929526, 2020). "Evaluation of adaptive immune cell profiles in the setting of combined TMZ and anti-CD47 treatment demonstrated a significant increase in both CD4+ and CD8+ T cells within the tumor." (PMID 32198351, 2020). "Depletion of CD4+ cells indeed abrogates the therapeutic efficacy, demonstrating ZD55-IL-24 can activate the tumor-infiltrating CD4+ T cells, which help tumor rejection." (PMID 33257647, 2020). "An increase in the proportion of CD4+ and CD8+ T cells was also seen in tumor-infiltrating lymphocytes of these mice." (PMID 33419310, 2020). "Altogether, these data pointed at inability of TERT2-specific T cells to eradicate TERT-expressing (tumor) cells and limit tumor growth and even indicated a promotion of tumor growth by TERT2-specific CD4+ cells." (PMID 32570805, 2020). "A deletion of GARP on platelets of mice showed a blunted TGF-β activity, which improved the CD4+ and CD8+ T cell immune response at the site of the tumor." (PMID 33291452, 2020). "We will give a brief review of the interplay between the cellular components of the adaptive immune response (T helper cells, also known as CD4+ T cells and cytotoxic T cells, also known as CD8+ T cells) during tumor progression." (PMID 32391271, 2020). "Since the final CAR-T cell product is a mix of CD4+ CAR-T and CD8+ CAR-T cells, another mean to refine this approach is to characterize the T cell subset that mediates anti-tumor activity." (PMID 33154756, 2020). "Genetic ablation of other complement proteins such as C3 was also shown to have profound inhibitory effects on primary tumor growth and metastasis correlating to increased numbers of IFNγ+/TNFα+/IL10+ CD4+ and CD8+ T-cells." (PMID 33718121, 2020). "We found that CD8+ and CD4 TILs were significantly increased in the PDT group and the PDT + BMS202 group in both LLC and MC 38 tumor tissue samples." (PMID 33472175, 2020). "TERT-specific CD4 T cells would nevertheless enable other responses by providing an initial attack on tumor cells and/or helping the expansion of CD4 and CD8 T cells with different tumor antigen specificities (epitope spreading)." (PMID 32630460, 2020). "Next, we examined the necessary contribution of the different lymphocyte subsets by selective depletion of CD4 and CD8 T cells in bilateral MC38 tumor‐bearing mice." (PMID 31746149, 2020). "There were significant increases in TUNEL positivity and localization levels of CD4+ and CD8+ cells on day 10, which corresponded to an increased detection of anti-tumor and immunosuppressive cells within the treated 4T1 tumors compared to controls." (PMID 32033171, 2020). "In contrast, the frequency of CD4+CD39+ Treg (p < 0.05) and of double-positive CD4+CD39+CD73+ T cells (p < 0.0001) was increased in the tumor tissue as compared to peripheral blood." (PMID 32082401, 2020). "Because tumor-infiltrating CD62L+ cells expressed Bcl6, we assessed the role of Bcl6 using Cd4-Cre/Bcl6-floxed mice." (PMID 32845913, 2020). "This lower Treg presence in Treg‐specific USP44knockout mice was accompanied by enhanced levels of pro‐inflammatory cytokine production within the CD4+ and CD8+ T cell compartments of the spleen, tumor‐draining lymph nodes, and tumors." (PMID 32644293, 2020).
tumor (continued). "A single dose of Aza resulted in increased infiltration of both CD4+ and CD8+ T cells throughout tumor tissue compared to DMSO-treated tumors." (PMID 32296439, 2020). "Initially, phenotypic analysis was performed to explore CD3, CD4, CD56, PD-1 and CTLA-4 expression on CIK cells and PD-L1/PD-L2 expression on tumor cells." (PMID 32349280, 2020). "Additional evidence of the dose-dependent PD-1 upregulation on CD4 and CD8 T-cells as well as PD-L1 upregulation on tumor cells and T-cells upon CEA-TCB treatment was obtained from in vitro experiments." (PMID 33330050, 2020). "Consistently, the analysis of tumor microenvironment composition showed a significantly higher abundance of CD8+ T-cells and Tregs, and a lower rate of CD4+ T-cells." (PMID 32670260, 2020). "The anti-tumor effect of heat-inactivated MVA requires CD8+ T cells, and the long-term anti-tumor memory response requires CD4+ T cells." (PMID 32245497, 2020). "In both tumor models, CED-TMZ and immunizations with the exception of CED-TMZ monotherapy in the KR158 model increased the influx of both CD8+ and CD4+ T-cells." (PMID 31900109, 2020). "By contrast, the presence of high CD4+ and low CD8+ tumor-infiltrating lymphocyte levels were independent predictors of poor progression-free survival (PFS), while the former was positively correlated with late tumor stage." (PMID 33123120, 2020). "Results of this interaction include upregulated expression of caspases, CD95 (Fas) and secretion of CD95 ligand (Fas ligand), and TNF-related apoptosis-inducing ligand (TRAIL), and enhanced detection of tumor cells by CD8+ and CD4+ T cells." (PMID 32033490, 2020). "Combined PD-1/CTLA-4 blockade inhibited tumor growth, stimulated the response of T cells to EBV pepmix, and enhanced CD4+ and CD8+ T cell infiltration in tumors." (PMID 33102204, 2020). "The CD4+ regulatory T cells (Tregs) are characterized by the expression of Forkhead Box P3(FOXP3) and CD25+ and are commonly described as tumor-promoting TILs." (PMID 32235370, 2020). "Of note, the same group successfully used tumor antigen-specific RNA-LPXs to trigger endogenous CD4 and CD8 T cell-mediated destruction of antigen-presenting tumor cells in mice and patients." (PMID 32942725, 2020). "The TME in orthotopic grown tumors revealed a larger population of tumor-infiltrating lymphocytes (TIL) with more B cells and CD4+ T cells than the subcutaneously grown tumors." (PMID 33383676, 2020). "We first analyzed ChIP-Seq datasets for H3K27me3 in non-tumor breast cell line MCF10A, prostate epithelial (PrEC) cell, CD4+ T cell, primary mammary epithelial (HMEC) cell, and human epidermal melanocytes (HEM) cell." (PMID 33144558, 2020). "The analysis of tumor infiltrating lymphocytes showed an increase in CD8+ T cells and a concomitant decrease in CD4+ T cells, positively correlating with the therapeutic outcome." (PMID 32290265, 2020). "Six different colored chromogens were utilized to label T-cells (CD3, CD4, CD8), B-cells (CD20), macrophages (CD16), and tumor cells (K17) in formalin-fixed paraffin-embedded (FFPE) PDAC tissue sections." (PMID 32723384, 2020). "Although we focused mostly on CD4+ and CD8+ T cells in this paper, DP T cells and NK cells also infiltrated the tumour in this model." (PMID 32439888, 2020). "Although tumor eradication has classically been attributed to CD8+ cytotoxic T cells, it is increasingly recognized that CD4+T cells also play an important role in tumor control." (PMID 33362774, 2020). "Immune subsets were characterized for CD4, CD8, FOXP3, CD20, CD33, and PD1 using immuno-fluorescence staining in stroma, tumor, and combined stroma and tumor tissue." (PMID 32150594, 2020). "Animal studies showed that combined transfer of tumour-specific CD8+ Tc and CD4+ Th cells significantly enhanced anti-tumour response, suggesting that both T cell subsets act synergistically and improve effectiveness of ACT in cancer patients." (PMID 32183246, 2020).
tumor (continued). "For each case, an average number of total TILs as well as CD4+ and CD8+ TILs, the percentage of TILs of each component, and the percentage of positive PD1 and PDL1 expression in both tumor cells and TIL was evaluated." (PMID 32811533, 2020). "On the contrary, the absence Gal1 gene in oncogenic KrasG12D-driven PDAC tumor in mice retained an increased number of CD3+, CD4+, CD8+ T lymphocytes, and decreased levels of CD11b+Gr1+ MDSCs in TME." (PMID 32823814, 2020). "We previously observed strong tissue infiltration of CD4+ T cells in tumor-free Rag2−/−γc−/− mice after adoptive transfer of EwS-redirected CD8+ T cells combined with PBMC, suggesting also a pivotal role of CD4+ T cells in tumor control in our model." (PMID 32610710, 2020). "Metacluster 1 (CD4 cells), 2 (macrophages) and 3 (CD8/B cells) showed significantly higher frequency in tumor-bearing sample while metacluster 4 (CD11c+ microglia) and 5 (CD115+ microglia) showed significantly higher frequency in naïve brain samples." (PMID 32764562, 2020). "We also show that the frequency of PD1+CD4+ T cells increases post-ASCT and in RRMM, particularly within the CD4+ TCM cell subset, which would be expected to impede tumor surveillance and DC vaccination." (PMID 33013907, 2020). "Here, we set out to identify the role of G-CSF and its receptor, G-CSFR, in CD4+ and CD8+ T cell responses in the tumor microenvironment." (PMID 33042110, 2020). "Taken together, these studies gave strong support to the real helper nature of CD4+ T cells in initiating and supporting the anti-tumor immune response, provided that they were triggered by CIITA-driven MHC-II+ tumor cells." (PMID 33138029, 2020). "We also found increased frequencies of Th1+ CD4+ T cells in HCC patients, particularly in the tumor itself, showing an efficient recruitment of these cells and an ongoing cytotoxic response in the tumor." (PMID 32182707, 2020). "In tumor-bearing mice, the percentage of A2aR was significantly increased in CD8+ T cells (P= 0.0046), with a similar trend in CD4+ T cells." (PMID 32721947, 2020). "An apparent rise in recruitment of DCs, tumor-infiltrating CTL (CD8+ and CD4+), and as well as a substantial decrease in Treg cells is reported when paired with PDT immunotherapy." (PMID 32865029, 2020). "Mice treated with pembrolizumab showed an escalation of exhausted T cells expressing TIM-3, and LAG-3 in tissues, higher levels of several human cytokines in plasma and high densities of FoxP3+ regulatory CD4+ and CD8+ T cells in the tumor microenvironment." (PMID 33511078, 2020). "Two major mechanisms by which TEV can contribute to tumor evasion are the initiation of apoptosis in cytotoxic CD8+ T cells and the conversion of conventional CD4+ T cells into regulatory T cells." (PMID 32973812, 2020). "The abundant immunosuppressive environment promotes both conversion and proliferation of CD3+CD4+CD25− cells into CD4+CD25+FoxP3+ Tregs population, leading to immune suppression mediated by tumor release of EGFR-containing exosomes." (PMID 32760402, 2020). "In the lymphoid compartment, the key effector cells involved in balancing the tumor immunity are CD8+ T cells, NK cells, B cells, and CD4+ T cells." (PMID 32083005, 2020). "This suggests that the fraction of CD8+ TILs with reduced CD5 levels in the tumor microenvironment have higher levels of activation than CD5high/CD8+ TILs, while the situation with CD4+ TILs is more complex." (PMID 33584650, 2020). "Nonetheless, there was a significant reduction of immunofluorescence using both anti-CD4 and anti-CD8 antibodies in the murine tumours exposed to exosomes indicating there is a reduced inflammatory phenotypic effect induced by each EV type." (PMID 32054041, 2020).
tumor (continued). "Flow cytometry analysis of tumor infiltrated leukocytes revealed that the DKK2 blockade did not significantly affect the infiltration of CD45+, CD4+ T cells, CD8+ T or natural killing (NK) cells in the tumors." (PMID 32559853, 2020). "Using tumour biopsies obtained prior to nivolumab treatment, tumour PD-L1 expression and CD8+ tumour-infiltrating immune cell expression were assessed, as well as stromal PD-1+, PD-L1+, CD3+, CD4+ and CD8+ immune cell expression." (PMID 32433601, 2020). "To further characterize CCR7 expression we also compared surface levels in our T-PLL cohort to the expression in different non-tumor T-cell subsets including CCR7-expressing TN and TCM cells (in both CD3+CD4+ and CD3+CD8+ subsets)." (PMID 33110606, 2020). "The positive percentage of CD4, CD8, and FOXP3 at the periphery of LM and tumor‐liver interface were 2.29, 1.08, and 0.09% in median, respectively." (PMID 32135041, 2020). "We demonstrated that HFD consumption obviously increased the frequencies of total, CD4+, and CD8+ T cells in tumor-seeded eFats." (PMID 33060562, 2020). "Irradiation also significantly increased expression of PD-1 on intratumor CD4+/CD8+ T cells and PD-L1 on tumor cells in tumor tissues." (PMID 32960261, 2020). "Since that the TIGIT/PVR immune checkpoint axis plays a major role in the functional regulation of T cells and NK cells, we also explored the role of CD4+, CD8+ T and NK cells in the tumor inhibition mediated by liothyronine therapy." (PMID 32894141, 2020). "Furthermore, IFN‐γ promotes the differentiation of naive CD4+ T into Th1 cells, stimulates the expression of MHC molecules presenting tumor antigens, mediates the cell cycle arrest, and increases the apoptosis and susceptibility of tumor cells to immune recognition and destruction." (PMID 32884708, 2020). "Flow cytometric analysis demonstrated that provision of hetIL-15 resulted in higher proportion of tumor-infiltrating CD8+ and CD4+ T lymphocytes, as well as NK cells harboring GzmB in comparison to untreated mice (respectively)." (PMID 32461349, 2020). "Next, we correlated the parameters of CD4+ and CD8+ T cell response to TERT1, 2, 6, 8, to tumor growth." (PMID 32570805, 2020). "By exploiting this platform, it has been shown that targeting CD4 and CD8 neo-antigen epitopes to Clec9A+ DCs in vivo effectively inhibits the growth of poorly immunogenic tumours." (PMID 33207697, 2020). "To validate the CD4/CD8 T‐cell enhanced effector function, as suggested by the in silico analysis, we analysed the expression of IFNγ, perforin and granzyme b in the tumour‐infiltrating lymphocyte populations by flow cytometry." (PMID 32567735, 2020). "On the other hand, immunization with SLP–Lpx stimulated both CD4+ and CD8+ T cells and suppressed tumor growth in a CD8+ T cell-dependent manner." (PMID 33298945, 2020). "T cell-mediated cytotoxicity, measured by contact-dependent detachment of adherent tumor cells, of STEAP1-specific CD4+ T cells (tgCD4) was initially observed after 46 days of culture." (PMID 32610710, 2020). "It is of note that for cancer patients whose tumor expressing MAGEA4 and MHC I, MAGEA4 vaccines can induce MAGEA4-specific immune responses to activate the CD4+ and CD8+ T cell resulting in the inhibition of tumor cell proliferation." (PMID 33287876, 2020). "We investigated the immune checkpoints PD1 and TIM3 expression on CD4+ and CD8+ T cells in the tumor microenvironment correlated with patient response to NAT." (PMID 32894006, 2020). "On the other hand, tumor immunogenicity was enhanced in the high TMB group, leading to significant infiltration of CD4+ memory T cells, M0/M1 macrophages, and dendritic cells as well as activated immune responses." (PMID 33234738, 2020). "In the tumor-bearing humanized mice, the percentages of tumor-infiltrating CD3+, CD4+ and CD8+ T cells were lower than those in blood and spleen, while there were no significant changes in the percentage of CD19+ B cells." (PMID 32331230, 2020).
tumor (continued). "Transfer of GCSFR−/− CD4+ and CD8+ cells yielded similar effects in reducing MC38 tumor growth when injected in Rag2−/− mice." (PMID 33042110, 2020). "Some cells that make up the tumor microenvironment, such as B, CD4, CD8, dendritic, macrophage, and neutrophil cells, have been shown in research to be correlated with the survival prognosis of many types of tumor patients." (PMID 32600423, 2020). "We observed the effect of asbestos fibers on T lymphocytes and found that anti-tumor immunity is attenuated in CD8+ cytotoxic T lymphocytes (CTLs), CD4+ helper T (Th), and regulatory T (Treg) cells." (PMID 32977478, 2020). "Intragastric administration of Shiquan-Yuzhen decoction in H22 tumor-bearing mice increased the thymus and spleen indices; upregulated the expression of CD3, CD4, CD8, and TNF-α receptors in lymphocytes; and decreased the expression of IL-2 and IFN-β." (PMID 32595757, 2020). "The association of the two treatments remarkably increases the amount of tumour-specific CD4+ and CD8+ T cells and increases the immune reaction against the tumour." (PMID 33704184, 2020). "On the other hand, low-dose anti-VEGFR2 treatment normalized tumor vessels with increased pericyte coverage, improved tumor perfusion, and eventually promoted the infiltration of CD8+ and CD4+ T cells into the tumor." (PMID 32913278, 2020). "The response was mainly driven by increased tumour-infiltrating CD8+ and CD4+ T cells and a reduced percentage of MDSCs76." (PMID 33116132, 2020). "In an immune inflamed tumor microenvironment, the tumor cells are in close proximity with the immune cells, such as monocytes, CD8/CD4 T cells and cells of myeloid origin and proinflammatory and effector cytokines." (PMID 33076303, 2020). "In this context, moDCs stimulated with supernatant of tumor cells treated with highly cytotoxic NB-PDT were able to enhance the proliferation and IFNγ production of CD4+ T cells, compared to untreated moDCs." (PMID 32326519, 2020). "Following a non‐specific restimulation with phorbol myristate acetate (PMA) and ionomycin, an augmentation in IL17‐producing CD4+, CD8+, and γδ T cells was observed in the tumor infiltrate (Fig EV3D–F)." (PMID 32323922, 2020). "Animal studies showed that antigen targeting to Clec9A induces strong anti-tumor immunity via the activation of CD8+ and CD4+ T cells." (PMID 32150821, 2020). "Consistent with an increased Th1 response, a trending increase in CD4+/IFNγ+ T cells and a significant increase in CD8+/IFNγ+ T cells per milligram tumor weight were observed in bintrafusp alfa-treated animals compared to controls." (PMID 32373533, 2020). "Staining of tumor sections with antibodies against CD3, CD4, CD8 and Foxp3 confirmed that the lymphocytes isolated on in vitro digestion were of intratumoral origin rather than peripherally associated with the excised tumors." (PMID 32461349, 2020). "In this study, we compared the effects of low-dose CTX at different time points on the expression of the anti-inflammatory cytokines IL-10 and TGF-β1, T-cell subsets including CD4+CD25+Foxp3+ T cells, and tumor immunity in mice." (PMID 32104586, 2020). "A functional enhancement of the CD4+ and CD8+ T cells will be needed to allow higher tumor infiltration and anti‐tumor responses." (PMID 32578942, 2020). "Here, we demonstrated that, besides conventional CD4+ and CD8+ T cells, IL36 surprisingly increased the number of tumor-infiltrating regulatory T (Treg) cells in vivo and enhanced proliferation of Tregs in vitro." (PMID 32351508, 2020). "Increased tumour size, less necrosis and reduced numbers of CD8+ Ki67 + and CD4+ IFN-γ+ cells were observed in mice injected with EGFR-19 del LLC EVs compared to wild-type EVs." (PMID 33143170, 2020). "Eradication of CD20hiB cells, enriched for a select population of CD20LO Bregs which escaped CD20-directed depletion and thus significantly suppressed CD4 + and CD8 + T cell activity thus abrogating anti-tumour responses." (PMID 31901949, 2020).